ESR1 (estrogen receptor 1)
Diseases named in the same sentence as ESR1 in open-access papers (continued):
Sharing a sentence is not in itself a finding about the gene and the disease.
liver fibrosis (20 papers, 2016 to 2025). "ESR1 in the liver was associated with stimulation of hepatocyte proliferation and was highly sensitive to liver fibrosis or hepatic fibrosis." (PMID 36561345, 2022). "The results further confirmed the effect of the high dose of THSW Decoction significantly increased JUN expression in the liver tissues of mice with liver fibrosis and decreased ESR1 expression." (PMID 40661312, 2025). "In addition, among all common targets for RGGs and liver fibrosis, ESR1, ESR2, AR, ACHE, CYP19A1, and AKR1B1 have a high degree of interaction with other targets and some active compounds." (PMID 35115923, 2021).
male infertility (20 papers, 2014 to 2025). The inability of the male to effect fertilization of an ovum after a specified period of unprotected intercourse. "Additionally, our study raises questions about the implications of ESR1 and GnRH1 gene mutations in male infertility, which warrant a more in-depth investigation." (PMID 37895049, 2023). "Furthermore, polymorphisms in exon 4 (LBD) of ESR1 also have a close association with male infertility." (PMID 34153045, 2021). "Association study between polymorphisms of the ESR1 (PvuII and XbaI) and ESR2 (RsaI and Alul) genes and male infertility suggested 3 times higher frequency of the heterozygous RsaI genotype in men with low sperm concentration compared to the controls." (PMID 29766145, 2018). "Similarly, the absence of ESR1 can lead to male infertility, which may be associated with abnormalities in the spermatogenic epithelium and spermatogenesis." (PMID 37235262, 2023).
adenoma (19 papers, 2008 to 2025). A neoplasm arising from the epithelium. "To explore this possibility we assessed the effects of Brg1 loss on Wnt-driven adenoma formation by driving recombination of the floxed Apc and Brg1 alleles with the Tg(Cyp1a1-cre/ESR1)1Dwi transgene, further abbreviated as AhCreERT." (PMID 25010414, 2014). "The proportion of adenoma and carcinoma subtypes was compared between Esr1 genotypes using Fisher’s exact test (2-sided)." (PMID 34068249, 2021). "FZD9-/- female mice exhibited higher mRNA levels of ESR1 and ESR2 in both whole lung and adenomas when compared to all male mouse groups and to wild-type female groups." (PMID 35924166, 2022). "Lower levels of methylation in carcinomas compared to adenomas have been described before for WIF-1 but also for other genes, such as p14 and ESR1." (PMID 24350795, 2013). "ESR1 has been shown to occur in histologically normal colon epithelium in an age dependent fashion, CDH13 is also frequently methylated in CRC and seems to be correlated with the adenoma-carcinoma transition, like other genes with methylation frequencies > 30% (CDKN2B, RASSF1, RARB, APC and TIMP3)." (PMID 25091577, 2014).
Impaired glucose tolerance (19 papers, 2010 to 2025). An abnormal resistance to glucose, i.e., a reduction in the ability to maintain glucose levels in the blood stream within normal limits following oral or intravenous administration of glucose. "ESR1 deficiency could induce pyroptosis, impaired glucose tolerance, and reduce lipid accumulation in hepatocytes." (PMID 36866057, 2023). "Loss of function mutations in the human ESR1 gene result in a variety of skeletal phenotypes including tall stature, reduced BMD and cortical thinning, as well as impaired glucose tolerance and hyperinsulinemia." (PMID 26911590, 2016).
rheumatoid arthritis (18 papers, 2005 to 2026). A chronic, systemic autoimmune disorder characterized by inflammation in the synovial membranes and articular surfaces. "Leflunomide, an immunosuppressive disease-modifying anti-rheumatic drug whose efficacy is modulated by ESR1 gene polymorphisms, is the only drug identified with a direct use in active moderate to severe rheumatoid arthritis." (PMID 26156520, 2015). "After comparison with normal control patients, it was annotated that women with SLE, as well as those with rheumatoid arthritis, have DNA methylation in the proximal promoter of the estrogen receptor 1 (ESR1) gene, which codes for the extensively expressed estrogen receptor α." (PMID 40182929, 2025).
heart failure (17 papers, 2012 to 2024). Inability of the heart to pump blood at an adequate rate to meet tissue metabolic requirements. "However, unlike heart failure, MYC, ESR1 and HIF-1 pathway have main functions in TAAD." (PMID 37283588, 2023).
viral infection (17 papers, 2016 to 2026). "During a transcriptional profiling study of Influenza A infection in lung epithelial cells, however, ESR1 was noted as a gene whose regulation was altered during NS1 deletion mutant viral infection." (PMID 31136639, 2019). "After viral infection and subsequent Cipa treatment we observe that the inhibitory effect of Cipa was diminished in ESR1-knockdown compared to mock-treated cells suggesting that DENV inhibition due to Cipa may be ESR1-dependent in MCF7 cells." (PMID 34635729, 2021). "However, the synergy between ESR1 and NF-κB during viral infection has not been extensively studied." (PMID 31136639, 2019).
gynecological cancers (16 papers, 2007 to 2026). "Studies indicate that mutations in the ESR1 gene may be a mechanism of resistance to aromatase inhibitor treatment in gynecological cancers." (PMID 40429755, 2025). "Whole transcriptome sequencing detected ESR1 fusion genes in 2.1% (n = 55/2574) of BC samples and in 1.9% (n = 21/1110) of gynecologic cancer samples, and CCDC170 was the most common fusion partner in both cancer types." (PMID 41555446, 2026). "The combined prognostic value (ESR1/EERES) may be applicable to other gynecologic cancers." (PMID 38582811, 2024). "Functional analysis substantiated that 39 of these genes played key roles in tumor initiation and cancer progression, with 2 specific genes (ESR1 and PGR) being shared across the gynecologic cancers." (PMID 38248117, 2024).
Hyperinsulinemia (16 papers, 2011 to 2025). An increased concentration of insulin in the blood. "At the anterior pituitary level, peripheral hyperinsulinemia may contribute to the GnRH-stimulated LH hypersecretion and restoration of pituitary ESR1 expression is likely a mechanism by which insulin sensitizer treatment prevents LH hypersecretion in prenatal testosterone sheep." (PMID 36755919, 2023).
psoriasis (16 papers, 2020 to 2025). An autoimmune condition characterized by red, well-delineated plaques with silvery scales that are usually on the extensor surfaces and scalp. "Furthermore, the underlying mechanism of the catalytic therapy for psoriasis is the up-regulation of estrogen receptor 1 (ESR1) in the FeN4O2-SACs treatment, which is largely reduced in the clinical samples of psoriasis and relapse patients." (PMID 37880231, 2023). "IHC results verify that the ESR1 level is lower in psoriatic and recurrent lesions than in normal skin, indicating the clinical responsibility of ESR1 deficiency in psoriasis pathology and that FeN4O2-SACs may ameliorate psoriasis and avoid relapse by restoring ESR1." (PMID 37880231, 2023). "In psoriasis, the binding sites of estrogen receptor‐1 (ESR1) are enriched with genes possessing anti‐apoptotic functions." (PMID 41385507, 2025). "By silencing ESR1 with shRNA (shESR1), aggravated cell proliferation and inflammation are observed in M5-induced psoriasis-like in vitro model, and notably, ROS-related hub gene upregulations can be seen." (PMID 37880231, 2023). "In summary, FeN4O2-SACs are highly effective in psoriasis control, hyperproliferation restraint, inflammation inhibition and ROS reduction by upregulating ESR1." (PMID 37880231, 2023). "Mechanistically, estrogen receptor 1 (ESR1) is identified as the core protein upregulated in psoriasis treatment through RNA sequencing and bioinformatic analysis." (PMID 37880231, 2023). "Two datasets (GSE52471, and GSE14905) related to psoriatic patients from the GEO database were adopted to evaluate the clinical relevance of ESR1, and 34 normal samples and 51 psoriasis samples were obtained." (PMID 37880231, 2023). "Genes correlating with the rather immature state of the keratinocytes in psoriasis, like ESR1, encoding for the estrogen receptor α which inhibits apoptosis, were found to be differentially expressed." (PMID 31973112, 2020). "Conversely, when the expression of ESR1 was knocked down using CRISPR/Cas9, FeN4O2-SACs treatment is not able to rescue the hyperproliferation and undue inflammation of M5-induced psoriasis-like in vitro model, indicating that ESR1 is indispensable for the curative effects of FeN4O2-SACs." (PMID 37880231, 2023). "Mechanistically, ESR1 deficiency has been identified by RNA sequencing and bioinformatic analysis to play a key role in psoriasis development and relapse, which, attractively, could be inhibited to large extents by FeN4O2-SACs treatment via ESR1 upregulation." (PMID 37880231, 2023). "Reportedly, ESR1 is the top-ranked hub gene, which is downregulated in psoriasis and related to anti-apoptotic functions, deeming it as a potential therapeutic target for psoriasis." (PMID 34168554, 2021). "recognized estrogen receptor 1 (ESR1), opioid receptor mu 1 (OPRM1), and hydroxysteroid 11-beta dehydrogenase 1 (HSD11B1) as promising therapeutic targets for psoriasis." (PMID 39883516, 2024). "Regarding the candidate targets, estrogen receptor (ESR1) showed the highest degree (113°), followed by PTGS2 (86°), NOS2 (81°), PPARG (60°), and GSK3B (56°), which demonstrated the potential therapeutic effect of each drug in LXJD formula for ameliorating psoriasis." (PMID 34168554, 2021).
Autoimmunity (15 papers, 2008 to 2023). The occurrence of an immune reaction against the organism's own cells or tissues. "Thus, the systemic deregulation of ESR1 and ESR2 genes found in CP/CPPS could indicate a dendritic cell mediated autoimmunity for CP/CPPS." (PMID 29731970, 2018).
esophageal cancer (15 papers, 2010 to 2024). A primary or metastatic malignant neoplasm involving the esophagus. "Furthermore, a survival plot showed that the high expression of some hub genes (FOXO3, CCR5, PECAM1, ESR1, and SMAD2) was associated with high risk of death in patients with esophageal carcinoma and other squamous cell carcinomas." (PMID 33747034, 2021). "A second therapeutic approach would be cell-based treatment that utilizes T-cell receptor (TCR)-engineered T cells to target ESR1 peptides, as has been done for gp100 and MART-1 peptides in the setting of metastatic melanoma and for MAGE-A4 peptide in the setting of esophageal cancer." (PMID 38335301, 2024). "The expression levels of ESR1 and ESR2 RNA (encoding ERα and ERβ protein, respectively) in esophageal cancer were not significantly different from those in the normal esophageal samples (p > 0.05)." (PMID 37762356, 2023). "The results showed that the RNA levels of ESR1 and ESR2 were not significantly different between esophageal cancer and normal esophagus, and were not correlated with the total survival time of the tumor patients." (PMID 37762356, 2023).
hyperlipidemia (15 papers, 2015 to 2025). "The PvuII T allele of ESR1 and associated genotypes and haplotypes are associated with risk of hyperlipidemia in postmenopausal Chinese Han females." (PMID 30217154, 2018). "The estrogen signaling pathway was regulated by CA binding to HSP90AA1, MMP2, RARA, PRKACA, ESR1, MMP9, and ESR2 in this present research, which underlies the improvements observed in hyperlipidemia and thrombosis." (PMID 38398534, 2024). "More importantly, AKT1, VEGFA, CCND1, ESR1 are the key targets of AM to alleviate hyperlipidemia induced by HFD." (PMID 35267929, 2022). "So far, we believe that AM may reduce the expression of AKT1 and CCND1 and increase the expression of VEGFA and ESR1 to alleviate hyperlipidemia induced by HFD." (PMID 35267929, 2022). "Supportably, it could be seen that AKT1 and CCND1, VEGFA and ESR1 were involved in hyperlipidemia-related diseases and several studies had uncovered the regulation of AM on these genes in different diseases." (PMID 35267929, 2022). "Through the analysis of the hub genes in the network, it was found that targets such as PIK3R3, GNB5, and ESR1(ERα) have higher MCC values, suggesting that these genes were important targets for improving hyperlipidemia in PCE." (PMID 34925692, 2021). "So far, we believe that AM may alleviate hyperlipidemia induced by HFD by downregulating the AKT1 and CCND1 protein levels and upregulating the levels of VEGFA and ESR1 protein." (PMID 35267929, 2022). "In conclusion, AM alleviated acquired hyperlipidemia in mice fed with HFD through regulating lipid metabolism, and AKT1, VEGFA, CCND1 and ESR1 may be the key targets." (PMID 35267929, 2022). "The previous bioinformatics analysis results showed that AM might alleviate hyperlipidemia by HFD through regulating the expression of four key targets (AKT1, VEGFA, CCND1 and ESR1)." (PMID 35267929, 2022). "The results of network pharmacology and bioinformatics analysis in the current study showed that AM might alleviate acquired hyperlipidemia by downregulating the expression of AKT1 and CCND1 and upregulating the expression of VEGFA and ESR1." (PMID 35267929, 2022). "Overall, AM alleviated acquired hyperlipidemia through regulating lipid metabolism, and AKT1, VEGFA, CCND1 and ESR1 might be the key targets." (PMID 35267929, 2022). "Similarly, ESR1(ERα), MAOA, MGAM, PTK2, MMP1, GNB5, PIK3R3, and other targets had higher degree values, suggesting that these genes might be the core targets of PCE intervention in hyperlipidemia." (PMID 34925692, 2021).
sarcoma (15 papers, 2007 to 2025). A usually aggressive malignant neoplasm of the soft tissue or bone. "TCGA study showed hypomethylation of ESR1 response genes, which was one of the uLMS unique features compared to other sarcomas included in this study (mainly soft tissue sarcoma)." (PMID 37373974, 2023). "The average ESR1 gene dosage in healthy breast tissues was 0.94±0.20, in pooled genomic DNA of healthy donors 1±0.05 and in ESR1-amplified sarcoma cell line 5.37±0.25." (PMID 23951298, 2013). "In fact, in GREB1-rearranged tumors, it has been reported that sex cord-like features are less represented than in ESR1-rearranged tumors; the term “GREB1-rearranged sarcoma” has also been proposed to distinguish these tumors from classical UTROSCT." (PMID 40150134, 2025).
preeclampsia (14 papers, 2018 to 2024). Preeclampsia is a hypertensive disorder of pregnancy that is characterized by new-onset hypertension with proteinuria presenting after 20 weeks of gestation, and depending on mild or severe forms may initially present with severe headache, visual disturbances, and hyperreflexia. "In humans, ESR1 gene expression and protein abundance were disrupted in the endometrium of patients with severe preeclampsia." (PMID 37234872, 2023). "The expression of ESR1 is reduced in preeclamptic placentas, whereas the placental expression of Erβ-encoding gene ESR2 is upregulated in preeclampsia." (PMID 34445328, 2021). "The expression of ESR1 in uterine arteries and placentas was reduced in preeclampsia and high-altitude pregnancy." (PMID 31671866, 2019). "In uterine arteries of pregnant sheep, hypermethylation of the ERα (ESR1) promoter during hypoxia reduced its expression, leading to preeclampsia and impaired cardiovascular homeostasis." (PMID 29649151, 2018). "Placental miR-22 was upregulated in preeclampsia and miR-22 binding to the 3′-UTR of ESR1 could repress ESR1 expression." (PMID 31671866, 2019).
prostate tumor (14 papers, 2007 to 2024). "Downregulation of ESR1 in osteocytes has been shown to regulate trabecular bone formation and thereby trabecular bone volume in male mice via these pathways, with subsequent bone loss being linked with disseminated prostate tumor cell growth." (PMID 38455075, 2024). "Prostate tumor and normal prostate tissues show elevated AR expression instead of ESR1 expression." (PMID 35594510, 2022). "Interestingly, among the common up-regulated targets, UGT2B15 and HOTAIR were described to be inhibited by AR in prostate tumors and activated by ESR1." (PMID 32041153, 2020). "We found a shift in the significance of the receptors for tumor recurrence; higher rates of AR expression are unfavorable for prostate tumor in younger patients, however it loses its significance in the oldest group, in contrast to ESR1, where higher expression is generally unfavorable." (PMID 29206234, 2017). "We analyzed TCGA gene expression profiles of 497 prostate tumor samples according to 43 genes involved in EMT and 3 hormone receptor genes (AR, ESR1, ESR2) as well as clinical characteristic of cancer patients." (PMID 29206234, 2017). "In the 4,490 prostate tumor biopsies, APUC-6 genes exhibited a robust correlation with one another, and all had strong positive correlations with ESR1, ESR2, and PGR (Spearman’s R 0.13–0.52), while the correlation with AR was relatively weak (Spearman’s R 0.06–0.20)." (PMID 39207857, 2024).
prostatic hyperplasia (14 papers, 2013 to 2026). "The cellular response to estrogen response is primarily mediated by ESR1 and ESR2, and changes in the expression profile of these receptors are related to the increased incidence of prostatic disorders, including PCa, with aging." (PMID 36499183, 2022).